SIRT6 (sirtuin 6)
Description:
NAD-dependent protein deacetylase, deacylase and mono-ADP-ribosyltransferase that plays an essential role in DNA damage repair, telomere maintenance, metabolic homeostasis, inflammation, tumorigenesis and aging. Displays protein-lysine deacetylase or defatty-acylase (demyristoylase and depalmitoylase) activity, depending on the context. Acts as a key histone deacetylase by catalyzing deacetylation of histone H3 at 'Lys-9', 'Lys-18' and 'Lys-56' (H3K9ac, H3K18ac and H3K56ac, respectively), suppressing target gene expression of several transcription factors, including NF-kappa-B. Acts as an inhibitor of transcription elongation by mediating deacetylation of H3K9ac and H3K56ac, preventing release of NELFE from chromatin and causing transcriptional pausing (By similarity). Involved in DNA repair by promoting double-strand break (DSB) repair: acts as a DSB sensor by recognizing and binding DSB sites, leading to (1) recruitment of DNA repair proteins, such as SMARCA5/SNF2H, and (2) deacetylation of histone H3K9ac and H3K56ac. SIRT6 participation to DSB repair is probably involved in extension of life span (By similarity). Specifically deacetylates H3K18ac at pericentric heterochromatin, thereby maintaining pericentric heterochromatin silencing at centromeres and protecting against genomic instability and cellular senescence. Involved in telomere maintenance by catalyzing deacetylation of histone H3 in telomeric chromatin, regulating telomere position effect and telomere movement in response to DNA damage. Required for embryonic stem cell differentiation by mediating histone deacetylation of H3K9ac. Plays a major role in metabolism by regulating processes such as glycolysis, gluconeogenesis, insulin secretion and lipid metabolism. Inhibits glycolysis via histone deacetylase activity and by acting as a corepressor of the transcription factor HIF1A, thereby controlling the expression of multiple glycolytic genes (By similarity). Has tumor suppressor activity by repressing glycolysis, thereby inhibiting the Warburg effect. Also regulates glycolysis and tumorigenesis by mediating deacetylation and nuclear export of non-histone proteins, such as isoform M2 of PKM (PKM2). Acts as a negative regulator of gluconeogenesis by mediating deacetylation of non-histone proteins, such as FOXO1 and KAT2A/GCN5. Promotes beta-oxidation of fatty acids during fasting by catalyzing deacetylation of NCOA2, inducing coactivation of PPARA (By similarity). Acts as a regulator of lipid catabolism in brown adipocytes, both by catalyzing deacetylation of histones and non-histone proteins, such as FOXO1 (By similarity). Also acts as a regulator of circadian rhythms, both by regulating expression of clock-controlled genes involved in lipid and carbohydrate metabolism, and by catalyzing deacetylation of PER2 (By similarity). The defatty-acylase activity is specifically involved in regulation of protein secretion. Has high activity toward long-chain fatty acyl groups and mediates protein-lysine demyristoylation and depalmitoylation of target proteins, such as RRAS2 and TNF, thereby regulating their secretion. Also acts as a mono-ADP-ribosyltransferase by mediating mono-ADP-ribosylation of PARP1, TRIM28/KAP1 or SMARCC2/BAF170. Mono-ADP-ribosyltransferase activity is involved in DNA repair, cellular senescence, repression of LINE-1 retrotransposon elements and regulation of transcription.
Synonyms: hSIRT6; SIR2L6
Tractability: Small molecule: a structure with a bound ligand is known; a high-quality ligand is known; it has a high-quality binding pocket. PROTAC: UniProt records ubiquitination sites on it; ubiquitination databases record sites on it; its protein half-life has been measured; a small molecule that binds it is known.
Target class: Histone deacetylase; HDAC class III; Epigenetic regulator; Eraser
Gene: Protein-coding gene on chromosome 19 (4,174,109 to 4,182,599, reverse strand). Ensembl gene ENSG00000077463.
Subcellular location: Nucleus; Chromosome; Chromosome, telomere; Endoplasmic reticulum
Subcellular location (Human Protein Atlas): Nucleoplasm; Vesicles
Pathways (Reactome):
DNA Repair: Processing of DNA double-strand break ends
Signal Transduction: Pre-NOTCH Transcription and Translation
Gene Ontology:
Molecular function: chromatin binding; chromatin DNA binding; damaged DNA binding; DNA binding; DNA damage sensor activity; histone deacetylase activity, NAD-dependent; histone H3K18 deacetylase activity, NAD-dependent; histone H3K56 deacetylase activity, NAD-dependent; histone H3K9 deacetylase activity, hydrolytic mechanism; histone H3K9 deacetylase activity, NAD-dependent; lncRNA binding; NAD+-protein mono-ADP-ribosyltransferase activity; NAD+-protein-lysine ADP-ribosyltransferase activity; NAD-dependent protein demyristoylase activity; NAD-dependent protein depalmitoylase activity; NAD-dependent protein lysine deacetylase activity; nucleosome binding; protein binding; protein homodimerization activity; NAD+ binding; NAD+ poly-ADP-ribosyltransferase activity; NAD+-protein-arginine ADP-ribosyltransferase activity; TORC2 complex binding; transcription corepressor activity; zinc ion binding
Biological process: chromatin remodeling; determination of adult lifespan; double-strand break repair; negative regulation of cellular senescence; negative regulation of gene expression, epigenetic; negative regulation of gluconeogenesis; negative regulation of glycolytic process; negative regulation of protein localization to chromatin; negative regulation of transcription by RNA polymerase II; pericentric heterochromatin formation; positive regulation of blood vessel branching; positive regulation of chondrocyte proliferation; positive regulation of double-strand break repair; positive regulation of proteasomal ubiquitin-dependent protein catabolic process; positive regulation of protein export from nucleus; positive regulation of stem cell differentiation; positive regulation of stem cell population maintenance; positive regulation of telomere maintenance; positive regulation of vascular endothelial cell proliferation; protein deacetylation; protein delipidation; protein destabilization; protein import into nucleus; protein localization to site of double-strand break; regulation of double-strand break repair via homologous recombination; and 27 more
Cellular component: chromatin; chromosome; chromosome, subtelomeric region; endoplasmic reticulum; nucleolus; nucleoplasm; nucleus; pericentric heterochromatin; site of DNA damage; site of double-strand break; chromosome, telomeric region
Genetic constraint (gnomAD): Loss-of-function variants: 21 observed, 28.56 expected, observed/expected ratio (o/e) 0.74, 90% interval 0.52 to 1.06. The upper end of that interval is the gene's LOEUF score, 1.06, which puts it in group 4 of 6, group 1 being the genes least tolerant of losing a copy. Missense variants: 493 observed, 445.2 expected, observed/expected ratio (o/e) 1.11, 90% interval 1.03 to 1.19. Synonymous variants: 217 observed, 191.15 expected, observed/expected ratio (o/e) 1.14, 90% interval 1.01 to 1.27.
Homologues: Orthologues: chimpanzee SIRT6 (99% identical), macaque SIRT6 (99% identical), dog SIRT6 (93% identical), pig SIRT6 (91% identical), mouse Sirt6 (83% identical), rat Sirt6 (78% identical), tropical clawed frog sirt6 (67% identical), zebrafish sirt6 (62% identical), Drosophila melanogaster Sirt6 (43% identical), Caenorhabditis elegans sir-2.4 (30% identical). Paralogues in human: SIRT7 (37% identical), SIRT4 (22% identical), SIRT3 (20% identical), SIRT1 (20% identical), SIRT5 (18% identical), SIRT2 (17% identical).
Diseases named in the same sentence as SIRT6 in open-access papers:
SIRT6 is named in the same sentence as 303 diseases in open-access papers, as found by Europe PMC text mining. Sharing a sentence is not in itself a finding about the gene and the disease. The quoted sentences say what the papers report.
Obesity (63 papers, 2011 to 2025). Accumulation of substantial excess body fat. "As mentioned, obesity is a significant risk factor for hepatic fibrogenesis, and we recently presented evidence that overexpression of centenarian-associated SIRT6 variants displayed anti-fibrotic impact in 3-dimensional in vitro models." (PMID 39033117, 2024). "Recently, a number of studies have linked SIRT6 enzymatic activities to obesity co-morbidities such as dyslipidemia, MAFLD, diabetes and cardiovascular diseases." (PMID 39033117, 2024). "Aging and excessive caloric intake, which are two major risk factors for obesity and diabetes, lead to decreased SIRT6 levels." (PMID 37928271, 2023). "This suggests a protective role of SIRT6 against metabolic consequences of obesity caused by an improper diet." (PMID 37298604, 2023). "Further experiments have indicated that mice with SIRT6 knockout were more susceptible to high-fat diet-induced obesity, attributed to adipocyte hypertrophy." (PMID 37298604, 2023). "Sirt6-deficient mouse models showed severe metabolic disorders, including elevated insulin resistance, high serum triglyceride levels and obesity, suggesting important roles of SIRT6 in glucose, lipid and energy metabolism." (PMID 36465178, 2022). "SIRT6 likely plays a role in metabolism, as SIRT6 deletion ultimately results in obesity; however, the underlying mechanism of its function has to be elucidated yet." (PMID 33806509, 2021). "SIRT6 is a nuclear protein associated with physiological and pathological processes, regulating obesity, insulin resistance, inflammation and energy metabolism." (PMID 33572672, 2021). "SIRT6 FKO mice are sensitive to obesity induced by an HFD, which is caused by fat cell hypertrophy rather than adipocyte hyperplasia." (PMID 33274005, 2020). "Studies have shown that the overexpression of SIRT6 in mice prevents metabolic diseases associated with diet-induced obesity." (PMID 33274005, 2020). "It supports the idea of a prominent role for SIRT6 as a potential therapeutic target for the treatment of obesity and associated disease, particularly liver disease." (PMID 30671172, 2018). "Aging and overnutrition, two major risk factors for obesity and diabetes, lead to decreased Sirt6 level and function, which results in abnormal glucose and lipid metabolism." (PMID 29535637, 2018). "Aging and overnutrition, two major risk factors for obesity and diabetes, lead to decreased Sirt6 level and function and result in abnormal glucose and lipid metabolism." (PMID 29535637, 2018). "A recent report highlighted that SIRT6 deficiency in fat tissue predisposes mice to obesity, insulin resistance and hepatosteatosis." (PMID 29786646, 2018). "SIRT6 deficiency results in liver steatosis and accelerates insulin resistance and obesity induced by diet." (PMID 30559718, 2018). "Accordingly, SIRT6-overexpressing mice are protected from diet-induced obesity and liver-specific deletion of SIRT6 in mice causes fatty liver formation." (PMID 29786646, 2018). "SIRT6 has been demonstrated to exert protective effects on endothelial cells and is closely associated with lipid metabolism, glucose metabolism, and obesity, indicating an important role in the pathogenesis and progression of coronary artery disease (CAD)." (PMID 27118880, 2016). "Interestingly, knock-out (KO) of SIRT6 in the rodent adipose tissue worsens obesity and associated insulin resistance, while its transgenic overexpression exerted a protective action against obesity." (PMID 39033117, 2024). "Furthermore, myeloid Sirt6 deficiency led to obesity-associated tissue inflammation and subsequent insulin resistance and macrophage infiltration." (PMID 36465178, 2022). "At present, seven mammalian sirtuins (SIRT 1-7) have been identified, with SIRT1 and SIRT6 shown to exert their metabolic actions in the hypothalamus, both with crucial roles in eliciting responses to dampen metabolic complications associated with obesity." (PMID 33572672, 2021).
Obesity (continued). "Myeloid Sirt6 is critical for preventing HFD-induced obesity and associated AT inflammation." (PMID 34493807, 2021). "Moreover, SIRT1 and SIRT6 have been implicated in obesity, insulin resistance, type 2 diabetes mellitus (T2DM), fatty liver disease and cardiovascular diseases." (PMID 30574122, 2018). "Adipocyte hypertrophy in Sirt6-deficient mice might be attributed to impaired lipolytic activity, which causes fat storage synthesis exceeding lipolysis and results in obesity." (PMID 29535637, 2018). "Sirt6 deficiency leads to liver steatosis and promotes diet-induced obesity and insulin resistance." (PMID 29535637, 2018). "To determine whether Sirt6 expression in visceral adipose tissue is associated with the degree of obesity, we examined the correlation between Sirt6 expression level and physical parameters of adiposity and quantitative traits of metabolic diseases in nondiabetic subjects." (PMID 31113929, 2019). "SIRT6 controls healthy ageing by regulating genomic stability, oxidative stress, and glucose metabolism, and it is considered a promising target for age-associated diseases such as chronic inflammation, diseases associated with metabolic syndrome, obesity, and insulin resistant type-2 diabetes." (PMID 28635654, 2017). "It is worth noting that a number of studies on animal models indicate decreased SIRT6 activity in the context of obesity and diabetes." (PMID 39861104, 2025). "Because SIRT6 regulates ENDOG/SOD2, it helps reduce myocardial oxidative stress caused by obesity resulting from a high-fat diet." (PMID 41567643, 2025). "By regulating each other’s activity, Sirt6 and Sirt3 shield the heart against diabetes-mediated cardiomyopathy brought on by obesity." (PMID 41567643, 2025). "The best documented actions of SIRT6 are on regulation of energy homeostasis, making it a potential therapeutic target for both obesity and cachexia." (PMID 39971710, 2025). "For example, supraphysiological overexpression of SIRT6 in hypothalamic neurons promotes diet-induced obesity, highlighting the tissue specificity of its actions." (PMID 41354870, 2025). "In obesity and diabetes animal models, SIRT6 suppresses liver gluconeogenesis genes and ameliorates hyperglycaemia by controlling PGC‐1α." (PMID 39971710, 2025). "In this context, attention has been paid to the participation of SIRT6 in the regulation of IR, obesity, and energy metabolism." (PMID 39861104, 2025). "The Sirt6 LKO mice gained more weight when compared with Sirt6 Floxed in this obesity model (Fig. EV5E)." (PMID 38332150, 2024). "In Sirt6 LKO mice with obesity background, we have found reduced CD4+ and CD8+ T cells in the liver." (PMID 38332150, 2024). "Sirt6 deletion in adipose tissue impairs the thermogenic function of BAT, causing morphological ''whitening'' of brown fat, reduced oxygen consumption, obesity, decreased core body temperature, and cold sensitivity." (PMID 37928271, 2023). "Our findings further elucidated the mechanism of the microglia Sirt6 for oxidative stress and inflammatory responses, thereby providing novel insights into how the CNS defend against obesity induced by a HFD." (PMID 37582706, 2023). "Subsequent studies established that Sirt6 transgenic mice were resistant to high-fat diet-induced obesity, manifested by less fat accumulation." (PMID 37582706, 2023). "Chrysophanol administration in mice with HFD-induced obesity substantially elevates SIRT6 and UCP-1 expression within WAT." (PMID 38053837, 2023). "Consistent with the results of this study, others have shown that diabetes and obesity reduce the expression of Sirt1, Sirt2, Sirt3, and Sirt6." (PMID 38134189, 2023).
Obesity (continued). "Sirt6 ameliorated long-term high-fat diet-induced obesity, altered microglia polarity, and alleviated the inflammatory response in the hypothalamus." (PMID 37582706, 2023). "In an analogous manner, hepatic-specific ablation of Sirt6 in mice increases liver steatosis while neural-specific deletion of Sirt6 in mice promotes diet-induced obesity and insulin resistance." (PMID 37497437, 2023). "Systemic SIRT6 overexpression protected mice from developing obesity and insulin resistance when fed with the HF-HS diet, and the hearts of these mice were also protected from mitochondrial fragmentation and SIRT3 downregulation." (PMID 38016059, 2023). "Collectively, these discoveries highlight the therapeutic potential of chrysophanol in combating obesity and related metabolic disorders by virtue of its ability to upregulate SIRT6, subsequently promoting the upregulation of PGC-1α and UCP-1 in BAT." (PMID 38053837, 2023). "Collectively, our results revealed that microglial Sirt6 was a primary contributor of microglial activation in the central regulation of obesity." (PMID 37582706, 2023). "Our findings extend the role of SIRT6 in the regulation of TNFα-mediated inflammation to chronic inflammation and glucose management during obesity." (PMID 35150745, 2022). "Consistent with this, we also found a significant protection against hyperglycemia, strongly suggesting that conditional SIRT6 deletion in macrophages once obesity is established prevents systemic inflammation and hyperglycemia." (PMID 35150745, 2022). "We found that SIRT6 downregulation in macrophages after the onset of obesity, decreased systemic inflammation and TNFα secretion, as well as improved glucose management." (PMID 35150745, 2022). "This not only extends our findings on a proinflammatory role of SIRT6 to chronic inflammation during obesity but also opens a plausible therapeutic window for treating inflammation and hyperglycemia during this disease." (PMID 35150745, 2022). "To test the possible role of SIRT6 on TNFα secretion after the onset of chronic inflammation during obesity, we developed a genetic mouse model for inducible SIRT6 deletion in macrophage colony-stimulating factor receptor 1 (Csf1r)–positive macrophages." (PMID 35150745, 2022). "Of note, SIRT1 and SIRT2 exert a dual effect on the progression of DM, while SIRT6 overexpression exacerbates diet-induced obesity." (PMID 36581622, 2022). "Fat-specific SIRT6 knockout sensitized mice to HFD-induced obesity, which was attributed to adipocyte hypertrophy instead of adipocyte hyperplasia by decreasing expression of ATGL." (PMID 36505468, 2022). "Overall, these findings suggest that high expression of SIRT1 and SIRT3 and low expression of SIRT2 and SIRT6 produced a metabolic state that inhibited the development of obesity, thereby reducing the occurrence of obesity." (PMID 36581622, 2022). "We found that Sirt6loxp/loxp;Cre− mice had significantly higher levels of secreted TNFα in the peritoneal cavity than Sirt6loxp/loxp;Cre + mice, confirming that SIRT6 deletion in macrophages ameliorates TNFα secretion in vivo during obesity." (PMID 35150745, 2022). "Recent work has shown that pharmacological SIRT6 inhibition ameliorates glucose intolerance and tissue damage during obesity, although this effect was ascribed to nuclear control of the expression of glycolytic genes." (PMID 35150745, 2022). "SIRT6 is mainly involved in protection against ischemia, reperfusion injury, obesity and insulin resistance." (PMID 33806509, 2021). "SIRT6 also protected from diet-induced obesity: systemic overexpression of Sirt6 decreased fat pads in high-fat diet-treated mice." (PMID 34712151, 2021).